CCL22 (C-C motif chemokine ligand 22)
Diseases named in the same sentence as CCL22 in open-access papers (continued):
Sharing a sentence is not in itself a finding about the gene and the disease.
tumor (continued). "Tregs are a crucial therapeutic target in the TME, they can be recruited to the TME by macrophages and tumor-derived factors such as CXCL12, CCL17 CCL22 and CCL1, thus suppressing the activation of T cells." (PMID 37656220, 2023). "Among CCL chemokines, CCL2, 3, 4, 7, and 8 were significantly less secreted by tumor tissues, while CCL17, CCL20, and CCL22 were secreted in higher concentrations in tumor as compared to juxta-tumor tissues." (PMID 36539890, 2022). "Tumour cells or infiltrating innate leukocytes release chemokines such as CCL17 and CCL22 to promote the migration of thymic Tregs expressing receptors such as CCR4, CCR5, and CCR8 from the secondary lymphoid tissues to the site of tumour." (PMID 35493450, 2022). "For example, in the presence of C-C Motif Chemokine Ligand 22 (CCL22) and C-C Motif Chemokine Ligand 28 (CCL28), Tregs are further promoted into the tumor cells." (PMID 36569915, 2022). "Th17 cells are generated by tumor-derived IL1β and IL13, and accumulate in tumor tissues in response to various chemokines, including CCL2, CCL5, CCL20, CCL17, CCL22, and MIF, which are produced from tumor cells." (PMID 36211375, 2022). "GBM tumor cells assist the recruitment and maintenance of Tregs in the TME by secreting soluble molecules such as CCL22, and the number of Tregs has been shown to have an inverse rapport with patient survival." (PMID 35269652, 2022). "In agreement, a recent study identified a four gene antitumor signature related to the tumor microenvironment, which included RIPOR2, CCL22, PAMR1, and FBN1 genes." (PMID 36497200, 2022). "Here, we show that out of a variety of human EBV+ tumor-derived cells lines, only those of B-lymphoma origin that express LMP1 also secreted both CCL17 and CCL22 at high levels in vitro." (PMID 35025968, 2022). "CCL22, a Treg-recruiting chemokine, was another chemokine that was increased in the ACKR2-decreased tumor tissues, showing that ACKR2 downregulation also promotes tumor development by creating an immunosuppressive tumor microenvironment." (PMID 35677043, 2022). "CCL17 and CCL22 are the ligands for CCR4, which effect on the recruitment of Treg, Th2, and Th17 into the tumor." (PMID 35517862, 2022). "T cell-rich tumors are correlated with better overall survival (OS) and were associated with the increased expression of IL-2, IFN-γ, and lymphocyte-attracting chemokines within the tumor such as CXCL9, CCL21, and CCL22." (PMID 36142615, 2022). "Chemokine ligands CCL17 and CCL22 present in TME facilitate the infiltration and accumulation of Tregs in tumor tissue through chemokine receptor 4 (CCR4), a G protein-coupled receptor, primarily expressed on the most immunosuppressive Tregs population." (PMID 36613878, 2022). "The macrophage-derived chemokine (MDC=CCL22) is secreted by the macrophages and OC cells of MA, which attract Tregs to the tumor, suppressing T cell immunity and enhancing tumor growth." (PMID 36142615, 2022). "It is important to note that the CD4-IL2RAhi- and CD4-IL2RAhi-CCL22+-Treg subtypes were already present in the pre-NACT tumors and persisted in all residual tumor samples after NACT therapy." (PMID 35907904, 2022). "RAB42 transcriptional expression was positively correlated with immune chemokines such as CCL22 and CCL2, which can be secreted by tumor cells to recruit the Tregs and TAMs respectively into the TME." (PMID 35720121, 2022). "In BCC, the expressions of PDGFR and prolyl-4-hydroxylase mRNA were augmented among the CAF activation markers, leading to increased CAF-related chemokines CCL17, CCL18, CCL22, CCL15, CXCL12, and IL-6 in both the tumor site and peritumoral skin." (PMID 35409404, 2022). "Here, we show some EBV+ tumor cells express high levels of the chemokines CCL17 and CCL22 both in vitro and in vivo and that this expression mirrors the expression levels of expression of the EBV LMP1 gene in vitro." (PMID 35025968, 2022).
tumor (continued). "This review briefly characterizes CCR4 and its ligands (CCL17, CCL22, and CCL2), and their contributions to immunological and neoplastic diseases." (PMID 36555280, 2022). "The receptor CCR4 has low expression on CD8+ T cells, but its ligands CCL22 and CCL17 recruit pro-tumoural TH2 and regulatory T cells to the tumour to support tumour growth." (PMID 35205725, 2022). "CCL22 and CCL17 were significantly downregulated cytokines in PRAME-deleted tumor samples, emphasizing the role of PRAME in TME crosstalk." (PMID 35380993, 2022). "M2-Mφs suppress tumor immunity and accelerate tumor progression by secreting immune suppressive factors, such as cytokines (TGF-β and IL-10) and chemokines (CCL2, CCL17, CCL22, and CCL24)." (PMID 35155237, 2022). "The FOXP3+CCR4+ Tregs from breast cancer patients’ peripheral circulation infiltrate tumor site in response to TME-secreted CCL17 and CCL22." (PMID 35222362, 2022). "Simultaneous infection of stromal and tumor cells; Upregulation of Fez1 and Pycard; Downregulation of DLL-4, Angiopoietin 2, PECAM, Tie-1, and FOS EGR2, CREB-5, IL-6, Map2K1, CCL22, TIMD4 and CCL19." (PMID 35640930, 2022). "TAMs secrete factors such as CCL22, CXCL1, and PDGF, which bind to corresponding receptors on tumor cells, thereby promoting tumor growth and metastasis, as well as resistance to various cancer treatments." (PMID 35070992, 2021). "Evidence from recent studies suggests that CCL22 plays a role in recruiting Tregs to tumor sites by binding the CCR4 receptor, which further facilitates tumor progression." (PMID 33710805, 2021). "Tregs recruitment occurs through the binding of CCR4 on Tregs surface and CCL22 secreted by GBM tumour cells and CD163+ TAMs, under the induction of tumour-derived CCL20 and osteoprotegerin." (PMID 33804731, 2021). "Tumor-promoting TAMs, similarly to other TME cells, by the production of tumor-promoting factors, including VEGF, various cytokines (IL-10, CCL2, CCL17, CCL22, TGF-β), and matrix-degrading enzymes, facilitate the tumor invasion, angiogenesis, and spread." (PMID 34885122, 2021). "CCR4 ligands CCL22 and CCL17, each involved in Treg recruitment into the tumour microenvironment (TME), were comparatively decreased in mice treated with sitagliptin and were consistent with the observed decrease in Treg abundance." (PMID 33513866, 2021). "Strong positive-correlations (r > 0.5, p < 0.05) were observed between the expression of CXCL10 and CCL5 and CD8+ T cell abundance in tumours, while CCL17 and CCL22 were negatively correlated (r < −0.5, p < 0.05) with CD8+ T cell infiltration." (PMID 33925140, 2021). "For example, HER2-enriched BCs show high tumor expression of TGF-β, a cytokine also involved in Treg differentiation from CD4+Foxp3- T cells, and of C-C motif chemokine 22 (CCL22), which is involved in Treg recruitment." (PMID 34944971, 2021). "For instance, we detected an increase in CCL2, CCL22, and CCL24 levels in all tumor spheroids upon monocyte addition." (PMID 34451433, 2021). "In the tumor microenvironment, L1CAM expression correlated with Treg infiltration in ESCC by affecting CCL22 secretion." (PMID 33710805, 2021). "For instance, CCL17 and CCL22, acting on CCR4, can directly recruit Th2 cells at the tumor site, thus participating in the development of cancers." (PMID 34777634, 2021). "We did not identify a prognostic trend for FoxP3IM, possibly because cancer cells in the CT produce chemokines, such as CCL22 and CCR4, thus resulting in lower DC infiltration and recruitment of more FoxP3, and consequently favoring tumor growth." (PMID 33710816, 2021). "CircCHST15 located in the cytoplasm promoted tumor growth, down-regulated the expressions of miR-155-5p and miR-194-5p, and up-regulated the expressions of PD-L1, Ki-67, PCNA, CCL17, CCL22, IFN-γ, TNF-β, and IL-10." (PMID 33777742, 2021).
tumor (continued). "In addition, CD8+ CTL may upregulate the expression of PD-L1 (program death ligand-1) and indoleamine-2,3-dioxygenase in tumor cells, recruit Tregs in the tumor microenvironment, and then promote tumor immune escape by the production of CCL22 (C-C motif chemokine ligand 22) and IFN-γ." (PMID 34395318, 2021). "The production of CCL22 is induced by inflammatory soluble mediators present in the TME, such as tumor cell-derived IL-1α in CRC and PDAC." (PMID 33924428, 2021). "Tumor microenvironment components secrete immunosuppressive chemokines, such as CCL17 and CCL22, to attract Treg cells." (PMID 33648605, 2021). "Macrophages secrete a large number of chemokines such as CC-like chemokines CCL22 and CCL20, which induce Tregs to recruit to the tumor site, similarly DCs also induce Treg generation, and then promote the metastasis of cancer cells." (PMID 33306121, 2021). "The interaction between CCL22 and the CCR4 receptor is related to cell proliferation and tumor progression." (PMID 34452282, 2021). "Conventional TREG can be attracted to the GC through CCL22 secretion, impairing T CD4+ or CD8+ activation by tumor antigens, with a pro-tumoral consequence." (PMID 33562694, 2021). "In vivo, elevated miR-23a-3p restrained the volume and tumor of GC and reduced the expression of CCL22 and phosphorylated PIK3/Akt, while knockdown miR-23a-3p motivated tumor growth." (PMID 34874224, 2021). "Macrophage-derived chemokine CCL22 in the TME and malignant ascites facilitate Treg infiltration to the OvCa, which inhibits anti-tumor immunity." (PMID 34248988, 2021). "In a similar study it was shown that 4T1 cells in the primary tumor can enhance metastasis in the lungs by inducing the expression of TARC/CCL17 and MDC/CCL22 genes." (PMID 33777801, 2021). "Nine chemokines were detected in EBNA1+ tumor cells, and the results showed CCL20 and CCL22 overexpressed." (PMID 32573058, 2020). "We included both anti- and pro-inflammatory cytokines involved in tumor suppression such as TNF-α, IL-1β, and tumor promotion such as IL-10, CCL22, CXCL5, and TGF-β (selection of cytokines based on ref.)." (PMID 33267818, 2020). "Also, other fucoidans can downregulate some cytokines and chemokines (e.g., M2-type chemokine CCL22) to inhibit tumor cell migration and lymphocytes recruitment via NF-κB-dependent transcription, which may be a novel and promising mechanism for tumor immunotherapy." (PMID 32354032, 2020). "Secreted by M2 macrophages, CCL22 regulates the epithelial-mesenchymal transition (EMT) of CRC cells and promotes tumor resistance to chemotherapy." (PMID 33343640, 2020). "In ovarian cancer, Tregs were selectively recruited into the tumor tissue via CCL22 and CCL28 production by the tumor cells and subsequently, Treg-induced secretion of high amounts of VEGF-A to promote endothelial cell proliferation." (PMID 33343570, 2020). "In our study, AdIL-17A transduction also directly upregulated CCR4 expression on tumor cells and enhanced expression of two CCR4 ligands, CCL17 and CCL22 in the lung." (PMID 32770025, 2020). "But, a significant inverse correlation between miR‐23a and CCL22 or Foxp3 was found from HBV‐ tumor group and HBV+ tumor group." (PMID 31769216, 2020). "It develops in response to tumor-derived factors and releases IL10, IL12, TNFα, TNFβ, VEGF, CCL20, CCL22, and MMP9, thereby supporting tumor growth and metastases and acting as an immunosuppressant." (PMID 32900001, 2020). "When the chemokine (CCL22), which is a ligand for CCR4, is produced in tumor tissues, regulatory T cells accumulate in tumor tissues." (PMID 31623180, 2019). "We observed that Plasmodium infection significantly downregulated the expression of the chemokines CCL17 and CCL22 as well as their receptor, CCR4 in the tumor microenvironment further validating the reduction in the proportion of Tregs in the tumor tissues." (PMID 30979375, 2019).
tumor (continued). "MAIT cells in circulation have been shown to express receptors for IP-10 (CXCR3) and CCL22 (CCR4), respectively, rendering them receptive to these chemokines, however, what this means for anti-tumor immunity is currently unclear." (PMID 31354725, 2019). "Our results indicated that Plasmodium infection significantly inhibits the tumor secretions of GMCSF, IL-10, IL-6, CCL-17, and CCL-22 in vitro through exosomes-like vesicles released by infected red blood cells." (PMID 30979375, 2019). "It has been reported that CCL22 and CCR4 are also expressed in several types of tumor cells and Foxp3+ Treg, respectively." (PMID 30718772, 2019). "Factors such as CCL-2, CCL-5, CCL-17, CCL-22, CXCL-12, M-CSF, VEGF, and TGF-β synthesized by the tumor stroma aid in the recruitment of monocytes and subsets of T cells." (PMID 31134198, 2019). "Intraperitoneal injection of bexarotene significantly decreased expressions of CCL22, CXCL5, CXCL10, and p19 in the tumor microenvironment." (PMID 31616630, 2019). "Intraperitoneal administration of bexarotene significantly decreased expressions of CCL22, CXCL5, CXCL10, IL-4, and p19 mRNA in the tumor microenvironment." (PMID 31616630, 2019). "T cell-rich tumors correlated with delayed recurrence or death and were associated with increased expression of Interleukin-2 (IL-2), IFNγ and lymphocyte-attracting chemokines within the tumor such as CXCL9, CCL21, and CCL22." (PMID 30042343, 2018). "Once established, tumor-derived factors drive macrophages toward an immunosuppressive phenotype which impairs anti-tumor T cell activity, primarily through the secretion of anti-inflammatory cytokines/chemokines such as TGF-β, IL-10, CCL17, and CCL22." (PMID 30459812, 2018). "Chemokines and cytokines including CCL2, CXCL12, CSF1, CCL5, CCL22, IL6 and TGFB3 are secreted by primary tumor cells to recruit immune cells to escape from anti-tumor immune responses." (PMID 28591712, 2017). "PD-L1 tumor abundance was negatively correlated with the serum cytokine IL10 and positively correlated with CCL22." (PMID 28266500, 2017). "These cells can enhance tumor angiogenesis, immunosuppression, tumor cell invasion and metastasis via the production of different cytokines and chemokines such as VEGF-A, CCL17/CCL22, and EGF." (PMID 28848446, 2017). "IDH1 status was associated with numerically higher plasma macrophage-derived chemokine (MDC/CCL22), higher whole blood FOXP3, and reduced tumor CD3+ T cell counts." (PMID 28481241, 2017). "In an animal BC model, tumor cells were shown to induce production of chemokine ligands, especially CCL17 and CCL22, at secondary sites, leading to chemotaxis of both tumor and immune cells." (PMID 27990412, 2016). "FAP reduction decreased transcripts for IL-10, TGF-β, CCL5 and CCL22 from CD14+ cells, of which 20-40% were F4/80+ TAMs; CCL5 transcripts were also reduced in tumor cells." (PMID 26943036, 2016). "We found that increased recruitment could be attributed to higher CCL22 production by EBVaGC cells, decreased emigration caused by downregulated lymphocyte homing receptor CCR7 on the Treg surface, higher Treg proliferation rates and lower apoptosis rates at tumour sites." (PMID 26673957, 2015). "The chemoattractant properties of CCR4/CCL22 and CCR4/CCL17 for Treg cells were assessed using the Boyden chamber technique, to elucidate the potential mechanisms of Treg recruitment in tumor microenvironment." (PMID 26020249, 2015). "In patients with ovarian carcinoma, the host response to the tumor has been shown to be inhibited by Foxp3+CCR4+ Tregs recruited to the tumor by CCL17 and CCL22." (PMID 26197455, 2015). "Tregs express CCR4; abundant expression of CCL22, the ligand for CCR4, in the tumor microenvironment stimulates the tumor infiltration of Tregs." (PMID 26528477, 2015).
tumor (continued). "Treg cells induction and recruitment to the local tumor tissue via CCR4/CCL22 signalling and tumor-derived TGF-β suggests that there is cross-talk between Treg cells and the tumor, which possibly leads to increased survival and malignancy of the tumor." (PMID 26020249, 2015). "In human ovarian carcinoma, TAMs produce the chemokine CCL22, which is one of the CCR4 ligands, as a mediator for the trafficking of Tregs to the tumor." (PMID 25125485, 2014). "CC chemokine receptor 6 (CCR6) axis has an important role in recruiting Tregs to tumor sites in HCC; TGF-beta and macrophage-derived chemokine (CCL22) signaling pathways induce aggregation of Tregs at the tumor sites in HCC too." (PMID 25000974, 2014). "The secretion of chemokines, like CCL22 and CCL28, by tumor cells and the microenvironment contribute to the recruitment of immunosuppressive cells in the tumor." (PMID 24734218, 2014). "Implanted orthotopic primary tumors “remotely” stimulate the expression of CCL17 and CCL22 in the lungs, which attract both CCR4(+) Tregs and tumor cells." (PMID 25110692, 2014). "Our results strongly argue for that despite the fact that both CCL22 and TGF-β1 involve in the tumor infiltration of Tregs, only CCL22 expression can serve as an independent prognostic predictor of BC patient’s survival." (PMID 24124553, 2013). "Analysis of tumor-infiltrating CD45+ leukocytes showed consistent Lov-mediated upregulation of IFNγ and IL-1β (M1 markers) and downmodulation of IL-10, CD206 and CCL22 (M2 markers)." (PMID 24317954, 2013). "Secreted CCL22 binds to the C-C chemokine receptor 4 (CCR4) on circulating Tregs, that migrate into the tumor microenvironment." (PMID 24312199, 2013). "M2-like TAM have high levels of mannose receptor-1 (MRC1/CD206), arginase-1 (Arg1), IL-10 and chemokines CCL22 and CCL17, whereas anti-tumor M1-like TAM express high interferon (IFN)γ and IL-1α/β levels; TNFα marks both M1- and M2-polarized TAM." (PMID 24317954, 2013). "CCL2 produced by cancer cells recruits MDSCs into tumor and CCL22 produced by M2 macrophages recruits CCR4+ Tregs and Th2 cells into tumor and sentinel lymph nodes." (PMID 23755373, 2013). "Hypomethylated genes in the TNF network were cytokines (CCL3, CCL4, CCL7, CCL8, CCL22, IL21, IL17A, EBI3) that can either stimulate or inhibit tumor growth and progression." (PMID 22768131, 2012). "By day 7, IFNγ, CSF2, CXCL10, GZMB, PTGS2, TNFα, CD80, CCL22, IL12a, IL13, IL1b, IL6, NOS2, and CTLA4 were significantly upregulated in the tumor-bearing mice bladders and AGTR2 and GATA3 were downregulated." (PMID 22013484, 2011). "Furthermore, the neutralization of CCL17 or CCL22 could prevent Treg cell infiltration to tumor." (PMID 20111717, 2010). "Treg recruitment into the TME is accomplished via CCR4/CCL22 or CCR4/CCL17 pathways after interactions between CCR4+ Tregs and CCL22/CCL17 secreted by TAMs and tumor cells; as such, CCR4+ Tregs abundantly infiltrate the TME and are considered the most immunosuppressive subset of Tregs." (PMID 40649958, 2025). "Alternatively activated macrophages (M2) could secrete the cytokine C-C Motif Chemokine Ligand 22 (CCL22), which enhanced tumor cell metastasis through the activation of the Smad pathway, as well as the upregulation of Snail." (PMID 40264760, 2025). "However, CCL22 produced by tumor cells or other cells in the TME can attract Tregs, which contribute to the suppression of anti‐tumor immunity." (PMID 40145607, 2025). "TAMs produce the chemokine CCL22, which recruits Tregs to the TME and reduces anti-tumour immunity." (PMID 38475858, 2024). "Fucosan can inhibit the tumour cell migration that is induced by the M2 macrophage conditioned medium, the function of CD4+ T lymphocytes, and especially the recruitment of Tregs by inhibiting CCL22 via the activity of NF-κB, which reduces CCL22 production." (PMID 38475858, 2024).